FOXP3 (forkhead box P3)
Diseases named in the same sentence as FOXP3 in open-access papers (continued):
Sharing a sentence is not in itself a finding about the gene and the disease.
tumor (continued). "Cx43 channels have also been involved in the regulation of T cell maturation and proliferation, in particular of CD4/Foxp3 double positive regulatory T cells and in the cross-presentation of tumor or viral peptides between cells." (PMID 25815348, 2015). "The present study identified a new subset of FOXP3+CD3+CD56+ cells occurring at a high frequency in the tumor tissue of HCC patients." (PMID 26437631, 2015). "An increase in the total pixel count of tumor-infiltrating immune cells was often reflected in higher pixel count for Tbet+ (r = 0.267, p = 0.061; Pearson) and Foxp3+ cells (r = 0.414, p = 0.005; Pearson)." (PMID 26357849, 2015). "Instead, CXCR3 marks a population of activated Foxp3− and Foxp3+ T cells, which use multiple and overlapping ligand receptor pairs to guide their migration to tumours." (PMID 25495686, 2015). "Spearman's correlation coefficients showed significant positive correlations between each other except for the correlation between the FOXP3 density in the tumor center and that in the invasion front (p = 0.165)." (PMID 25875774, 2015). "This chemokine, having bound to the CCR4 receptor, directed migration of CD4 + CD25 + FOXP3+ lymphocytes toward neoplasm." (PMID 26077607, 2015). "A randomized phase II biomarker study found that baseline tumor expression of FoxP3 and IDO correlates with clinical activity of ipilimumab, as does high TIL count." (PMID 29546098, 2015). "With regard to BCSS, CD8+ TIL, the CD8/FOXP3 ratio, residual tumor size, and nodal status after NAC were significantly correlated with survival in the univariate analyses." (PMID 26341640, 2015). "The potent immunosuppressive activities of FOXP3-expressing CD3+CD56+ cells prompted an inquiry into the clinical relevance of their prevalence in tumor tissues." (PMID 26437631, 2015). "FoxP3+ regulatory CD4+ T-cells (Tregs) are another subset of functionally immunosuppressive hematopoietic cells that infiltrate the HNSCC tumor microenvironment and suppress effector T-cells via a number of mechanisms." (PMID 26690220, 2015). "In patients with hepatocellular carcinoma and liver metastases from colon cancer, the number of CD25+FoxP3+ Tregs is significantly higher in tumours than that in tumour-free liver tissue." (PMID 25961057, 2015). "The results reported in recent studies suggest that FOXP3 is not only expressed by lymphocytes, but is also expressed by normal epithelial cells and tumor cells." (PMID 26305693, 2015). "And the predominant compositions of FOXP3+ T cells in tumor tissues are quite different, thereby leading to different prognoses." (PMID 26305693, 2015). "As expected, numbers of CD4+ T cells, CD8+ T cells and CD4+FoxP3+ T regulatory cells were reduced 3 days after Cy administration (day 11 post tumor inoculation)." (PMID 26082836, 2015). "In contrast to the other T cell subsets, FoxP3+CD4+ Treg subpopulation had a constantly higher proportion (10-40%) in CD4+ T cell subsets from initial stage to late stage with the tumor progression." (PMID 25968569, 2015). "In conclusion, our meta-analysis suggests that the prognostic role of FoxP3+ Tregs was highly influenced by tumor site, and was also correlated with the molecular subtype and tumor stage." (PMID 26462617, 2015). "The proportion of CD4+CD25+FoxP3+ Tregs in the periphery seems to increase with tumor burden, and depletion of this population prior to challenge in the A20 lymphoma mouse model resulted in 70% tumor-free survival." (PMID 25941795, 2015). "We confirmed this result with Western blot analysis, suggesting the presence of Foxp3-expressing macrophages in other organs in context of the tumor being present." (PMID 25264896, 2014). "We recently have observed that increased expression of PD-L1, IDO, and FoxP3+ Tregs in the melanoma tumor microenvironment is driven by infiltrating CD8+ T cells, arguing that these mechanisms are part of an immune-intrinsic negative feedback loop." (PMID 24829760, 2014).
tumor (continued). "We propose that low level FOXP3 expression is advantageous to the tumor, possibly by providing immune suppressive function, in keeping with previous studies." (PMID 24406338, 2014). "Recently emerging articles have investigated the correlation between tumor-infiltrating Foxp3+ cells and clinical prognosis in various kinds of tumors, indicating discrepant results on how these TILs really predict patient outcome." (PMID 24276989, 2014). "The rs3761548 polymorphism of FOXP3 gene was evaluated in 50 TNBC patients and in 115 neoplasia free controls." (PMID 24877082, 2014). "This consistence indicated a similar ratio of the nTregs (demethylated TSDR status) with Tregs (FOXP3+) in tumor tissues versus normal tissues." (PMID 24938080, 2014). "The different CD8+:TREG ratios and the presence of FOXP3+ cell subsets of undetermined identity in the tumor microenvironment have been proposed as probable explanations." (PMID 24778636, 2014). "The density of FOXP3+ lymphocytes in local tumor tissue correlated significantly with the histological grade and overall lymph node status." (PMID 25191901, 2014). "Increasing evidence demonstrated that the frequency and activity of CD4+ CD25+ FoxP3+ Tregs increased in the circulation and tumor microenvironment in patients with various types of cancer." (PMID 24264641, 2014). "Of the examined characteristics, only the intratumoral abundance of Foxp3+ T cells was correlated with tumor differentiation, the pathologic tumor status, tumor stage and lymphatic invasion." (PMID 24637664, 2014). "IDO expressed by plasmacytoid DCs (pDCs) present in tumor-draining lymph nodes can directly activate FoxP3+ Treg cells." (PMID 24587363, 2014). "One of their remarkable findings was the opposite prognostic significance of high densities of FOXP3+ Tregs in tumor tissues (better survival) and in adjacent normal mucosa (worse survival)." (PMID 24938080, 2014). "We demonstrated here that significant Foxp3 expression was found only in tumor infiltrating macrophages." (PMID 25264896, 2014). "Our findings suggested that tumor-infiltrating FoxP3+ T cells were a factor for a poor prognosis for HCC and GC, but a good prognosis for CRC." (PMID 24827118, 2014). "Multivariate analysis showing HR for patient RFS conferred by nodal status, tumor size, nuclear grade, higher numbers of Foxp3-positive TIL and higher expression of B7-H3." (PMID 24562936, 2014). "Tumour associated macrophages or myeloid-derived suppressive cells, CD4+ Foxp3+ Treg cells and Th17 cells and their associated cytokines Il-6, TNF, IL-1β, IL-23 and TGF-β are generally recognized as dominant tumour-promoting forces." (PMID 24963981, 2014). "FOXP3-expressing cells in cancer settings have been correlated with poor anti-tumor effector response, hence compromising tumor immunity." (PMID 25099367, 2014). "Several additional lines of evidence suggest a tumor suppressor role for FOXP3 in certain tumor types." (PMID 24406338, 2014). "To confirm these findings and examine the correlation between tumor-infiltrating Foxp3+ T cells and the clinicopathologic PDA characteristics, we examined the Foxp3+ T cell abundance in PDA tissues from 160 patients and five control specimens." (PMID 24637664, 2014). "We also analyzed the correlation of density of FOXP3+ lymphocytes in lymph nodes with the nodal status and distance from the primary tumor." (PMID 25191901, 2014). "To date, no meta-analysis has been undertaken for any studies that evaluate tumor-infiltrating FoxP3+ T cells as a prognostic marker in HCC, CRC or GC." (PMID 24827118, 2014). "Foxp3+ TILs as well as CD8+ ones were detected by immunohistochemistry on paraffin-embedded tumor samples from 62 patients." (PMID 24276989, 2014). "In this study, we analyzed a FOXP3 polymorphism (rs3761548) in 50 TNBC patients and in 115 controls free of neoplasia." (PMID 24877082, 2014).
tumor (continued). "This was attributed to effacement and thus ‘dilution’ of normal lymphoid tissue by tumor cells, prompting further examination of FOXP3 expression specifically within the T cell population of BCL, RH and MCT cases." (PMID 25119018, 2014). "Recently, CD4+Foxp3+ Tregs in tumor tissue were reported to have significantly increased compared with normal lung tissue." (PMID 24868562, 2014). "We examined the association of MMP-23 with the anti-tumor immune response - as assessed by the prevalence of tumor-infiltrating lymphocytes and Foxp3+ regulatory T cells." (PMID 25491880, 2014). "There was a tendency for the proportion of FOXP3 expression to positively correlate with tumor stage." (PMID 25170840, 2014). "In the present work, we analyzed the tumoral protein expression of FOXP3 and found that 83% of the patients had a strong expression of this protein in the tumor microenvironment." (PMID 24877082, 2014). "FoxP3+ Treg cells were mainly present within the tumor area, but less frequently they gathered in groups surrounding the tumor." (PMID 25365237, 2014). "In the context of the expression of Foxp3 in the tumor infiltrating lymphocytes, it is likely that the SIRT1 effects a reduction in the suppressive function of these T regulatory cells which is likely to be reversed by vorinostat." (PMID 24395633, 2014). "To address this possibility in our model, we evaluated Treg frequencies using FoxP3 intracellular flow cytometry analysis in the lymphoid organs and within the tumor." (PMID 24829760, 2014). "Foxp3 high was observed significantly more often in tumors with positive nodal status (p < 0.001), large tumor size (p < 0.05), high histological grade (p = 0.002), or HER2 overexpression (p = 0.001)." (PMID 24562936, 2014). "As expected, the anti-CD25 mAb-treatment group significantly depleted the CD4+CD25+FoxP3+ cell population in both the tumor and spleen." (PMID 25034887, 2014). "The migration of the T cells positive for CD3, CD8 or FOXP3 into the tumor sites was reported to be correlated with the outcome of patients with several types of malignancies (i.e., ovarian, colorectal, and breast cancer as well as head and neck cancer) [8.9]." (PMID 25461761, 2014). "Two different antibodies, available commercially, with non-overlapping epitopes on the Foxp3 protein (clone FJK-16S AA75-AA125 and clone NRRF-30 AA1-AA75), recognise Foxp3 in Renca tumor infiltrating macrophages, mainly in the M2 population." (PMID 25264896, 2014). "The controversy concerning expression of Foxp3 in cells other than Treg continued in other studies, but the tumor setting was minimally investigated." (PMID 25264896, 2014). "Tumor-infiltrating FoxP3+ T cells have been reported in various human tumors, which impaired cell-mediated immunity and promoted disease progression." (PMID 24827118, 2014). "There also have been several reports of FoxP3 expression through tumor cells themselves, which has been interpreted as a specific tumor escape mechanism." (PMID 25365237, 2014). "Adoptively-transferred Treg from tumor-bearing animals lose Foxp3 expression when treated with DTA-1, whereas Treg from naïve mice maintain Foxp3 expression." (PMID 25144375, 2014). "The presence of Foxp3+ cells in the tumor microenvironment is thought to inhibit host-protective antitumor responses and especially CTL activity." (PMID 24997850, 2014). "At least one FOXP3+ iTIL (intratumoral) was present in 45.0% and at least one sTIL (stromal) in 74.8% of the 3,277 tumor cases." (PMID 25193543, 2014). "Some reports in the literature suggest a potential oncogenic and tumor escape function of Foxp3 in tumor cells." (PMID 25264896, 2014). "CD4+CD25+Foxp3+ T cells were increasing with tumor development; however, values found in the LN from KO groups were significantly higher as compared with WT mice." (PMID 25268644, 2014).
tumor (continued). "Consistent with prior reports, FOXP3+ lymphocytes infiltrated the primary tumors, and were found scattered throughout the interstitial regions of the tumor." (PMID 25191901, 2014). "iv) The percentage and intensity of FoxP3 (O1–O3) positively correlated with L1CAM expression (P1+P2) in tumor cells." (PMID 24797069, 2014). "In intrahepatic CCA, the tumor-infiltrating lymphocytes IL-17+ and FOXP3+, CD66b+ neutrophils, and microvessels were predominantly found in the intratumor area, whereas CD8+ lymphocytes were most abundant in the tumor invasive front." (PMID 24901008, 2014). "There are 16 studies involving 1873 patients that compared the survival of HCC according to FoxP3+ T cells expression level of the primary tumor met the enrollment criteria." (PMID 24827118, 2014). "The data were organized according to overall survival and recurrence; then combined results strongly demonstrated that high density of tumor-infiltrating FoxP3+ T cells was a good prognosis for CRC." (PMID 24827118, 2014). "The decrease in the frequency of Foxp3+ cells in the HF10-treated group is possibly correlated with the decrease in tumor size due to HF10 treatment." (PMID 25105508, 2014). "Here we detected the expression of Foxp3 in tumor tissues obtained from 62 GBM patients and examined its predictive significance for clinical outcome." (PMID 24276989, 2014). "Foxp3 expression in tumor-infiltrating lymphocytes (TILs) correlated significantly with larger tumor size (>2 cm), expression of human epidermal growth factor receptor 2 (HER2), and higher nuclear grade (p = 0.003, p < 0.001, p = 0.001, respectively)." (PMID 24562936, 2014). "We require better understanding of the functional subtypes of FoxP3+ T cells and their biologic properties in different tumor microenvironments if we wish to rationally modulate their behavior to enhance tumor immunity." (PMID 24827118, 2014). "A multivariable analysis was performed for OS and DFS using the following parameters: age, TNM stage, tumor grade, adjuvant therapy, circumferential margin, HLA class I expression status, HLA-G expression status and Foxp3+ tumor infiltration." (PMID 24997850, 2014). "The result has challenged the conventionally theory that FoxP3+ T cells can suppress tumor immunity." (PMID 24827118, 2014). "In conclusion, our data demonstrate that the frequency of CD4+CD25+Foxp3+ Tregs is significantly increased in PDA tissue and that these cells inhibit tumor-associated antigen-specific CD8+ T cells." (PMID 24637664, 2014). "Forkhead box protein 3 (Foxp3) is known as a specific marker for regulatory T cells which contribute to immunosuppression in tumor microenvironment." (PMID 24276989, 2014). "After factoring in the lymph node status and local tumor density of FOXP3+ lymphocytes, multivariate analysis indicated the latter as having only borderline statistical significance." (PMID 25191901, 2014). "This tumor-induced increase in FOXP3+ Tregs represents a potential barrier to attempts at cancer immunotherapy." (PMID 25193543, 2014). "Specifically, FOXP3 expression has been reported in normal breast, prostate and ovarian epithelium, and to be down-regulated in the corresponding tumor tissue." (PMID 24406338, 2014). "There was nearly a two-fold increase in the density of Foxp3(+) Treg cells in the metastatic node, compared with the non-tumor bearing lymph node." (PMID 24885770, 2014). "We have recently demonstrated that, in OSCC, tumor nests are infiltrated by distinct subsets of CD4+FOXP3+ regulatory T cells." (PMID 24465587, 2014). "We performed detailed investigations into Foxp3 expression in macrophages in the normal tissue and tumor settings." (PMID 25264896, 2014). "A significantly higher TSDR-DMR and FOXP3 mRNA as well as protein expression level were found in tumor sites versus normal ones, implying that abnormal recruitment of nTregs occurred at tumor sites." (PMID 24938080, 2014).
tumor (continued). "CD45RA and CCR7 expression patterns indicated that both LAP+ and LAP− subsets of Foxp3+CD4+ T cells mostly had an effector/memory phenotype in peripheral blood as well as in tumor sites of CRC patients." (PMID 25268580, 2014). "Concerning infiltrate of mononuclear cells expressing FOXP3 in the tumor microenvironment, we had the results of 38 patients and observed that 47% and 58% of these had a moderate or intense intratumoral and peritumoral infiltrated, respectively." (PMID 24877082, 2014). "Our results show that the combination therapy inhibited tumor growth at the contralateral as well as the injected tumor sites by promoting the accumulation of tumor-specific CD8+ T cells followed by DTA-1-mediated depletion of CD4+ Foxp3+ Treg cells." (PMID 25105508, 2014). "Marked differences between the metastatic node and tumor-regressed node were found in the incidence of Foxp3(+) regulatory T (Treg) cells and CD56(+) natural killer (NK) cells." (PMID 24885770, 2014). "In this patient set, the local tumor FOXP3+ lymphocytes density appeared to have greater prognostic value than even nodal status." (PMID 25191901, 2014). "This expression level indicates that FOXP3 transcripts are present in a sufficiently high number in tumor cells and caution should be exerted when detection of FOXP3 mRNA expression in surgical tumor samples is used as an index of tumor infiltration by Tregs." (PMID 24877082, 2014). "This study demonstrated that the numbers of Foxp3-positive cells was significantly increased among tumors with positive nodal status, large tumor size, high histological grade, and HER2 overexpression." (PMID 24562936, 2014). "Quantification of the frequency of FOXP3 positive cells showed this to range between 0.3 and 7.5 positive cells per 1000 tumor cells (0.03-0.75%)." (PMID 24406338, 2014). "In this stage, the tumor-inhibiting effect of CD8+ CTLs is suppressed by FOXP3+ Tregs, myeloid suppressor cells (MDSCs), neutrophils, M2 macrophages, Th2 CD4+ T cells and cytokines such as TGF-β, IL-6." (PMID 24743335, 2014). "In melanoma, deletion of CD45RA(−)FoxP3(hi)CD4(+) Tregs (effector Tregs) using anti-CCR4 antibody significantly augmented CD8(+) T cell infiltration in the tumor and unmasked a nascent antitumor host response." (PMID 25110692, 2014). "In contrast, FOXP3 has also been suggested to facilitate tumorigenesis by enabling tumor cells to evade anti-tumor immunity." (PMID 24406338, 2014). "A previous study suggested that tumor-expressed FOXP3 triggers a mechanism for the immune evasion of tumor cells." (PMID 24649219, 2013). "For example, a high number of CD4+CD25++Foxp3+ regulatory T-cells (Foxp3+Tregs) have been observed in the peripheral blood and tumor microenvironment of cancer patients." (PMID 23725550, 2013). "CCR5 deficiency (demonstrated by use of CCR5−/− mice) or CCL5 blockade (using Met-RANTES) led to diminished CD4+Foxp3+ T cells numbers and slower tumor growth." (PMID 23874342, 2013). "We have previously demonstrated that vaccination of mice with FOXP3 mRNA-transfected DCs elicits FOXP3-specific T cell responses and enhances tumor immunity." (PMID 23341929, 2013). "FOXP3 also induces expression of several tumor suppressors including p18 (CDKN2C), p21 (CDKN1A), LATS2, and ARHGAPS." (PMID 23341929, 2013). "But, on the other hand, FOXP3 has emerged as an important regulator of some oncogenes and as a tumor suppressor factor able to control cell proliferation of tumor cells." (PMID 24350059, 2013). "In 2009 Banissi and coworkers reported that low-dose metronomic TMZ regimens (0.5 and 2 mg/kg for 21 days) induced a significant decrease in Foxp3+Treg/CD4+ ratios in the spleen of tumor-bearing animals." (PMID 23725550, 2013). "In fact, patient survival has been shown to correlate negatively with tumor FoxP3+ Treg cell infiltration in small-cell lung cancer." (PMID 24216706, 2013).